S100A8 (S100 calcium binding protein A8)
Diseases named in the same sentence as S100A8 in open-access papers (continued):
Sharing a sentence is not in itself a finding about the gene and the disease.
periodontitis (38 papers, 2011 to 2025). An acute or chronic inflammatory process that affects the tissues that surround and support the teeth. "CRP and S100A8 were chosen as relevant markers of systemic inflammation associated with both periodontitis and CVD." (PMID 38667035, 2024). "Previously it has been reported that increased concentration of S100A8/A9 in saliva and serum were associated with periodontitis patients." (PMID 34372836, 2021). "Lots of studies have investigated the importance of genetic polymorphisms (e.g., MCP-1, S100A8, IL-1α, IL-1β, and N-formyl peptide receptor) in aggressive periodontitis." (PMID 28018430, 2016). "In the late stages, S100a8 and S100a9, which encode damage-associated molecular patterns, and Cxcl5 and Cxcl3, which encode chemokines, are prominently upregulated, highlighting the persistent recruitment of neutrophils, a hallmark of periodontitis." (PMID 40076622, 2025). "Elevated serum and salivary levels of S100A8/A9 were associated with periodontitis patients." (PMID 38667035, 2024). "Increased concentrations of salivary S100A8 were associated with elevated metalloproteinase-9 levels, which supports the possible use of these salivary biomarkers as a rapid test kit for the early detection of periodontitis." (PMID 38667035, 2024). "Polymorphisms in S100A8 gene were also associated with aggressive periodontitis." (PMID 35315933, 2022). "Salivary S100A8 could be a potential diagnostic marker for established periodontitis and be useful for screening established periodontitis." (PMID 34372836, 2021). "Periodontitis induced the development of GMPs toward the neutrophil lineage at the expense of monocytic differentiation, as indicated by the dynamic changes in monocytic signature genes (F13a1, Irf8, and Ly86) and neutrophil-associated genes (Camk1d, S100a8, and S100a9) along the trajectory." (PMID 40521205, 2025). "The best performing group to distinguish between health (or gingivitis) and periodontitis resulted in an AUC of 0.970 and included alpha‐1‐acid glycoprotein, matrix metalloproteinase‐9, pyruvate kinase, S100A8, and age." (PMID 39620241, 2025). "In this systematic review, three out of the 13 included studies reported higher S100A8 levels in periodontitis patients as compared to periodontally healthy controls." (PMID 39620241, 2025). "Recently, three targeted studies demonstrated significantly higher salivary levels of S100A8 in periodontitis patients as compared to healthy controls." (PMID 39620241, 2025). "Functional analysis revealed that both bacteria promoted the enrichment of proteins involved in the acute inflammatory response, including elevating IL-1α, IL-RN, and S100A8, which are key players in the immune response during periodontitis." (PMID 40574274, 2025). "As innate immune effectors in experimental periodontitis, S100A8 levels were elevated in the presence of bacteria in the junctional epithelium." (PMID 40574274, 2025). "Among them, complement C3, profilin‐1, S100A8, and fibrinogen were consistently increased in periodontitis cases." (PMID 39620241, 2025). "On the other hand, increased level of proteins S100-A8 and S100-A9 is treated as a marker of periodontitis, indicating that an imbalance of these 2 proteins can cause oral pathological states." (PMID 36949424, 2023). "S100A8, S100A9, S100A12, were all elevated in saliva from periodontitis and gingivitis patients compared to healthy controls and salivary levels of S100A8, S100A9 and S100A12 were significantly related to clinical and radiographic signs of periodontitis." (PMID 38098978, 2023). "In a recent study, it was discovered that salivary S100A8/A9 (calprotectin) was higher in gingivitis patients compared to healthy, and higher in periodontitis patients compared to healthy or gingivitis patients." (PMID 35315933, 2022).
periodontitis (continued). "The aim of our study was to evaluate the presence of S100A8/A9/A12, MMP8, and CFH polymorphisms in periodontitis and to find out if polymorphisms of these genes affect the concentrations of corresponding proteins or marker of complement activation in saliva." (PMID 35315933, 2022). "According to our knowledge, there are no other previous studies on the association between genetic polymorphisms of S100A8, S100A9, or S100A12 and periodontitis." (PMID 35315933, 2022). "As MMP‐8 is centrally involved in the pathogenesis of periodontitis, we aimed to evaluate the presence of genetic polymorphisms of S100A8/A9/A12, MMP8, and CFH in periodontitis." (PMID 35315933, 2022). "The intervention of periodontitis using periodontal treatment will elucidate the role of S100A8 on periodontitis prognosis." (PMID 34372836, 2021). "This study aimed to compare the association and screening ability of S100A8 and S100A9 in saliva, blood and gingival crevicular fluid (GCF) for periodontitis status." (PMID 34372836, 2021). "Our data showed that salivary S100A8 had the most appropriate screening ability for periodontitis among S100A8 and S100A9 in saliva, blood and GCF." (PMID 34372836, 2021). "Our data showed that the screening ability of S100A8 for established periodontitis was 0.73 of c-statistics, which was higher than the previous Korean study with 0.6 of c-statistics and a bit lower than Austrian calprotectin study with 0.86 of c-statistics." (PMID 34372836, 2021). "In a recent study, high levels of calprotectin were detected in gingival crevicular fluid (GCF) from patients with periodontitis, and high levels of S100A8 and S100A9 were also detected in blood vessels in Pg-infected mice." (PMID 32149126, 2020). "Lundy and colleagues, in line with other transcriptomics and proteomics studies, found increased expression levels of S100-A8 in periodontitis and gingivitis sites compared to the healthy ones." (PMID 32722327, 2020). "Increased levels of S100A8/A9 in gingival crevicular fluids of periodontitis patients induce IL-6 production of gingival fibroblasts via TLR4 signaling involving MAPK and NF-κB." (PMID 29942307, 2018). "We investigated whether the polymorphisms linked to serum MMP‐8 associate with periodontitis, periodontal parameters, and saliva concentrations of TCC, S100A8, and S100A12 in a well‐characterized, relatively large sample of middle‐aged or elderly participants." (PMID 35315933, 2022). "However, saliva levels of S100A8, S100A12, MMP‐8, and TCC, and CFH polymorphisms were associated with clinical and radiographic signs of periodontitis." (PMID 35315933, 2022). "In addition to saliva, also systemic concentration of the S100A8/A9 complex (calprotectin) was higher in aggressive periodontitis patients." (PMID 35315933, 2022). "Interestingly, periodontitis patients were clustered in two groups with either high or low levels of salivary S100A8/A9 at baseline." (PMID 35315933, 2022). "Calprotectin, S100A8/A9, is the marker for gingivitis and periodontitis." (PMID 34372836, 2021). "Hence, the present study aimed to compare the association and screening ability of S100A8 and S100A9 in saliva, blood and GCF according to the periodontitis status." (PMID 34372836, 2021). "The next step of Salivary S100A8 research should be focused on whether salivary S100A8 could be the prognostic marker for periodontitis." (PMID 34372836, 2021). "Since salivary S100A8 could be the best marker for periodontitis, a rapid test kit using salivary S100A8 could be effective on promoting periodontal health for general public." (PMID 34372836, 2021). "As to established periodontitis, salivary S100A8 could be the best consistent biological marker among S100A8 and S100A9 in saliva, GCF and blood." (PMID 34372836, 2021). "Overall, elevated level of salivary S100A8 protein concentration could be a valid marker for established periodontitis screening." (PMID 34372836, 2021).
periodontitis (continued). "Complement C3, keratin (type I and type II), profilin‐1, S100A8, cystatin‐SN, alpha‐2‐macroglobulin, leukocyte elastase inhibitor, and fibrinogen were the proteins consistently over‐expressed or under‐expressed in periodontitis patients in at least three papers." (PMID 39620241, 2025). "Moreover, the ratio S100A8/S100A9 in saliva can differentiate distinct groups of periodontitis." (PMID 37224160, 2023). "Salivary S100A8, S100A12, and MMP‐8 concentrations were associated with periodontitis, ABL, the number of periodontal pockets with PPD 4 to 5 mm, and especially the number of periodontal pockets with PPD ≥ 6 mm (OR for 10‐fold increase in S100A8: 4.22; 95% CI, 2.15 to 8.30; P < 0.001)." (PMID 35315933, 2022). "Thus, S100A8 salivary kit will be useful for screening established periodontitis." (PMID 34372836, 2021). "Similarly, GCF fluid containing S100A8 and S100A9 was associated with periodontitis." (PMID 34372836, 2021). "Thus, the hypothesis of this study was that S100A8 and S100A9 in saliva, blood and GCF show the difference in the association and screening ability of S100A8 and S100A9 in saliva, blood and GCF according to the periodontitis status." (PMID 34372836, 2021). "A number of these genes were also significantly increased in aging and periodontitis tissues (e.g., ANXA1, HMGB1, S100A8, S100A9, APOE/ß2-GPI, LTF, TSLP)." (PMID 38098978, 2023). "In recent years, saliva S100A8 and S100A9 have been shown to be promising biomarkers for periodontitis." (PMID 35315933, 2022). "T-test, analysis of covariance, Mann–Whitney test and correlation analysis were applied to compare the relationship of S100A8 and S100A9 in saliva, blood, and GCF for periodontitis." (PMID 34372836, 2021). "The adjusted value of S100A8 in saliva, after controlling for confounders, was also higher by 1.6 and 1.8 times in stage II and stage III–IV periodontitis participants than in NIPERIO participants (ANCOVA, p < 0.05)." (PMID 34372836, 2021). "In the present study, we focused on the effects of S100A8 and S100A9 on expressions of proinflammatory- and bone metabolism-related factors in osteocytes to elucidate mechanisms in aggravation of periodontitis." (PMID 32149126, 2020). "Taken together, S100A8 and S100A9, in periodontal tissue, have essential roles for the progression of periodontitis." (PMID 31605018, 2019). "Additionally increased levels of S100A8/A9 could be observed in serum of patients with varied diseases concerning the bowel, the joints, the heart, the skin, and multiple other organs, and enhanced S100A8/A9 levels have been observed in crevicular fluid of patients suffering from periodontitis." (PMID 29180834, 2017). "In accordance with a previous report, myeloperoxidase, myosin 9, annexin A3, profilin-1, L-plastin (plastin-2/LCP1), S100A8, and S100A9 were detected at higher levels in chronic periodontitis patients compared to healthy individuals." (PMID 21794177, 2011). "Common biomarkers of periodontitis and RA activity include calprotectin (CLP), also known as a myeloid-related protein (MRP-8/14) or leukocyte protein L1, which is a heterodimer formed by two calcium-binding proteins S100A8 and S100A9." (PMID 38248363, 2024). "Salivary S100A12 was also elevated in both periodontitis and gingivitis groups compared to control groups, but no significant change was found in the levels of S100A8/A9 (calprotectin) and S100A12 after nonsurgical periodontal therapy." (PMID 35315933, 2022). "Although the measured saliva concentrations of TCC, S100A8, and S100A12 were significantly higher in periodontitis, the corresponding genetic polymorphisms did not correlate with the saliva levels." (PMID 35315933, 2022). "Among the studied polymorphisms of CFH, MMP8, and S100A8/S100A9/S100A12 gene region, those located in the CFH gene associated with periodontitis, whereas the ones near S100A9 or in the MMP8 gene did not." (PMID 35315933, 2022).
periodontitis (continued). "However, the adjusted values of S100A8 and S100A9 in GCF were higher by around 2.5 times in NIPERIO participants than in stage II and stage III–IV periodontitis participants (ANCOVA, p < 0.05)." (PMID 34372836, 2021). "Thus salivary S100A8 and S100A9 have been specific targets for researcher and practitioners who are interested to identify periodontitis using robust and cost-effective method." (PMID 34372836, 2021). "Interestingly, results showed an up-regulation of colony-stimulating factor-1 (CSF-1), S100A8/A9, S100A12, interleukin (IL)-1β, matrix metalloproteinase (MMP)-8, and hepatocyte growth factor (HGF), in patients with periodontitis with a statistical significance of p<0.001." (PMID 37224160, 2023). "Moreover, the ratio S100A8/S100A9 and the metalloproteinase-8 in saliva could differentiate distinct periodontitis groups." (PMID 37224160, 2023). "It was reported that the concentration of S100A8 in saliva was 1.6 and 1.8 times higher in participants with stage II and stage III–IV periodontitis compared to those without periodontitis." (PMID 38473012, 2024). "In blood, the adjusted value of S100A8 and S100A9 were not significantly different according to periodontitis status (ANCOVA, p > 0.05)." (PMID 34372836, 2021).
stomach cancer (37 papers, 2007 to 2025). "Here we show elevated S100A8 and 9 as well as arginase-1, suggesting enhanced MDSC activity in stomach tumors deficient in IL-1RT1 signaling." (PMID 25528766, 2015). "The increased expression of the PPARδ target gene, Agptl4, the TGFβ-activated genes Runx1 and Runx2, and S100A8 and S100A9 in the gastric tumors indeed suggests a duality of function of both PPARδ and TGFβ signaling in gastric tumorigenesis." (PMID 21318167, 2010). "Gene ontology analysis of gene expression in the gastric tumors indicates that PPARδ, MMP12, MMP13, Cxcl1, Cxcl5, S100A8, and S100A9 share both common and disparate pathway interactions that likely contributed to the tumorigenic phenotype." (PMID 21318167, 2010).
colorectal cancer (32 papers, 2009 to 2025). A primary or metastatic malignant neoplasm that affects the colon or rectum. "In prostate cancer, benign prostate hyperplasia, and colorectal cancer, serum S100A8 and S100A9 are shown to have diagnostic potential." (PMID 30808902, 2019). "Although previous studies on breast and colorectal cancers have associated high tumor S100A8 expression with aggressive features and poor outcomes, our data suggest that immune-related expression patterns may provide more meaningful insights into EC." (PMID 41303754, 2025). "However, it is worth noting that there is still a limited body of research on the role of S100A8/A9 in colorectal cancer cells and their associated mechanisms." (PMID 38817853, 2024). "In addition, several studies have suggested that increased S100A8/A9 expression in colorectal carcinoma may play a role in tumor progression and may be associated with metastasis and histological grade." (PMID 25371673, 2014). "Studies have consistently reported elevated S100A8/A9 expression in both inflammatory bowel disease and colorectal cancer tissues 21, 23-25." (PMID 38817853, 2024). "Particularly noteworthy is S100A8's involvement in establishing a self-reinforcing feedback loop typified by 'inflammation-tumor-inflammation' within colorectal cancer cells." (PMID 38817853, 2024). "Functional models of high S100A8/S100A9 expression in colorectal cancer cells were established through transfection with overexpression plasmids." (PMID 38817853, 2024). "We obtained the expression matrix for colorectal cancer patients from the TCGA database and conducted a differential analysis based on the expression levels of S100A8 and S100A9." (PMID 38817853, 2024). "It has been reported that the relatively high expression of S100A8 is found in infiltrating monocytes in human colorectal cancer specimens." (PMID 36932197, 2023). "S100A8 has also been discovered as a protooncogene in several malignancies, including lung cancer, colorectal cancer, and cholangiocarcinoma." (PMID 35646116, 2022). "S100A8/A9 expression was identified in tumor-infiltrating CD68+ macrophages in human colorectal cancer." (PMID 34209679, 2021). "S100A8 treatment can increase the viability and migration of colorectal carcinoma cells.We performed a series of experiments to evaluate the role of S100A8 in HCC." (PMID 27462864, 2016). "For this reason, increased expression of calcium-binding proteins S100A8 and A9, members of the S-100 protein family, in the peritumoral and intratumoral spaces in colorectal carcinoma becomes important for tumor progression." (PMID 25371673, 2014). "In colorectal carcinoma, tumoral tissues infiltrate with various immune/inflammatory cells along their invasive margins, and the increased S100A8/A9 expression in these immune cells infiltrating the tumor has recently been demonstrated by certain studies." (PMID 25371673, 2014). "This showed that Sec C could act as a promising clinical candidate in colorectal cancer treatment, and S100A8 could be a prospective drug target." (PMID 38607060, 2024). "Moreover, it was found that the S100A8/A9 complex can be used for the diagnosis or the evaluation of treatment and prognostic of colorectal cancer and Hodgkin’s lymphoma, which can also promote tumor cell apoptosis under inflammatory conditions." (PMID 36010914, 2022). "The neutrophil chemokine S100A8 is an important neutrophil attractor and chronic inflammation mediator in the lungs of CF mice which also contributes to colorectal cancer cell survival and migration via the Wnt/β-catenin pathway and consequent c-Myc expression." (PMID 35500936, 2022). "In our study, we investigated increased expression of S100A8/A9 in the tumor microenvironment in colorectal carcinoma as well as previously shown inflammatory process functions of S100A8/A9, which exhibits concentration-dependent function and forms a heterodimeric complex." (PMID 25371673, 2014).